CD68 (CD68 molecule)
Diseases named in the same sentence as CD68 in open-access papers (continued):
Sharing a sentence is not in itself a finding about the gene and the disease.
infection (continued). "While CD68, CD163, and Mac387 macrophages are all susceptible to SIV infection, Mac387 macrophages are the least susceptible to infection, possibly because these cells are relatively immature and express less CCR5." (PMID 35203323, 2022). "HP dams also had increased splenic CD68+ macrophage populations compared to LP dams following secondary infection, suggesting enhanced immunity at a cellular level." (PMID 35264261, 2022). "Under mock infection, the CD68 level of WT microglia was slightly lower than that of TM+/LeD microglia." (PMID 35277184, 2022). "When assessing signature synaptic pruning markers, C1qa and CD68, we detected an increase in gene expression persistent through the course of infection." (PMID 35898505, 2022). "When compared to the uninfected controls, the frequency of human CD4+ T cells in the vaginal mucosa, spleen and lung, and CD68+ macrophages in lung tissue of both the huNRG and huDRAG-A2 mice was significantly reduced at 8 weeks post-infection." (PMID 36146734, 2022). "Splenic macrophage population marked by CD68+ was increased in HP compared to LP dams following secondary infection of N. brasiliensis." (PMID 35264261, 2022). "Both expression level of CD68 and investigation of differentially expressed mRNAs in cardiac fibroblasts indicated that rGO/silk patch induced infection/immunity and pro-inflammation." (PMID 34485415, 2021). "From dpi 4, the total microglia population upregulated CD45, increased their granularity (side scatter - SSC-A) and progressively downregulated CX3CR1, F4/80 and CD68 over the course of infection." (PMID 34311763, 2021). "Although macrophages (CD68+) in the area of the infection or pyogranuloma were seen, it was difficult to ascertain if any of the B. pseudomallei HBPUB10134a were within the macrophages." (PMID 32365605, 2020). "It is still unclear, however, if human macrophages are directly infected by SARS-CoV-2, although we found virus antigen in CD68+ macrophages and others report infection in murine MAC2+ macrophages." (PMID 32841215, 2020). "To evaluate the phagocytic activity during infection and after treatment of the infected mice with IE, we examined the number of CD68-positive cells in liver sections." (PMID 30838089, 2019). "In this study, the infection of alveolar macrophages and AT-II cells in cynomolgus macaque were confirmed using Abs against CD68 and ACE2, respectively, accompanied with Abs against F. tularensis LPS." (PMID 31235714, 2019). "It is definite that Leishmania parasites interact and infect a variety of host cell types, CD68+ macrophages and CD1a DCs are the most important cells that regulate the outcome of infection." (PMID 29515633, 2017). "There was a significant increase in infiltrating cells into the peritoneal cavity of CD68(bcl2)tg mice 24 hours after infection with S. pyogenes." (PMID 27973535, 2016). "We do not believe that this detection represents phagocytosis of other WUPyV-infected cell types because WU-VP1, a late-expressed protein, was detected in the nucleus of CD68-positive cells, suggesting an infection in this patient." (PMID 26691850, 2016). "While there is a mild increase in bacterial load in lungs of infected CD68(bcl2)tg mice 96 hours after infection, the increased inflammation precedes this increase in bacterial burden." (PMID 27973535, 2016). "Given the impact that the CD68(bcl2)tg has on in vivo infection with L. pneumophila, we explored how L. pneumophila-induced PCD is affected by expression of bcl2 in relevant myeloid cell types." (PMID 27973535, 2016). "After infection CD68(bcl2)tg mice lose more weight and have a longer recovery time when compared to littermate controls." (PMID 27973535, 2016). "In order to determine if this increased lung damage was due to an increased bacterial burden in the lung of CD68(bcl2)tg mice we determined the colony forming units (CFUs) in the lungs from infected mice 1 hours, 48 hours, and 96 hours after infection." (PMID 27973535, 2016).
infection (continued). "Given the increase in different myeloid cell types during infection with S. pyogenes in CD68(bcl2)tg mice, the effect of ectopic expression of bcl2 on S. pyogenes-induced cell death was examined." (PMID 27973535, 2016). "We first optimized the preparation of H. pylori-infected targets by infecting THP-1 Mφ with H. pylori at different MOI (10, 20, 50, and 100) and evaluating the infection rates in differentiated (CD68+) vs. undifferentiated (CD68−) Mφ using an anti-H." (PMID 26441971, 2015). "By contrast strong cellular staining—presumably lytic infection—was confined (78/78 cells) to CD68+ macrophages." (PMID 25790477, 2015). "HCMV-infected monocytes exhibit gene expression changes that are associated with macrophage differentiation as early as four hours post infection and have an upregulation of macrophage markers, such as CD68, as early as 24 hours post infection." (PMID 24531335, 2014). "We observed a 5-fold increase (P = 0.0040) in the number of M1 macrophages (F4/80+ CD68+ IL-12+) in IKKβ cKO mice at 2 days post-infection." (PMID 23349802, 2013). "The time course study from 0 to 8 dpi based on 19F MRI and histological analysis of VACV-treated tumors revealed discrepancies between the spatio-temporal 19F accumulation and the CD68+-macrophage population during the course of infection." (PMID 23441176, 2013). "Infection of mice with SL3261 also led to increased expression of CD68 in perivascular macrophages and microglia, while in naïve mice, CD68 is conspicuously expressed in perivascular macrophages." (PMID 22738332, 2012). "As previously shown, macrophage (CD68) and dendritic cell (CD11c) infiltration into the heart of wt mice infected with the parasite peaks at 21 days post-infections." (PMID 22807679, 2012). "With the progression of the disease into the late phase (3 days after infection) the up-regulation of the marker CD68 reflects microglial differentiation into a macrophagic phenotype." (PMID 20565785, 2010). "A similar expression profile is observed for the macrophage specific marker CD68, which shows a pronounced up-regulation at 3 days after infection and is a correlative for the differentiation of microglia into mature macrophages." (PMID 20565785, 2010). "Co-localization of positively stained CD68+ cells with p24 in this organ was indicative of infection of cells of the myeloid lineage in mature and immature animals." (PMID 17266752, 2007). "K18-hACE2 mice revealed a 60% reduction in CD68+ cell recruitment to the site of infection relative to hACE2 mice, and only about 25% of CD68+ cells co-stained positive for SARS-CoV-2 negative strand, though negative strand staining in the airways was quite evident in these mice." (PMID 39763770, 2025). "Future work quantifying CD163 expression in the liver in addition to CD68 over the course of the infection in the cynomolgus macaque model used in this study would help clarify if the same pattern is present in both models or if these represent distinct immunologic responses." (PMID 39635525, 2024). "There was also a prominent increase in the marginal zone and white pulp macrophages such as marginal zone macrophages (MHCII+ CD209b+), marginal metallophilic macrophages (MHCII+ CD169+), and tingible body macrophages (MHCII+ CD68+) between day 7 and 11 post-infection." (PMID 39341498, 2024). "Thus, we examined the expression of activation markers: namely Iba1, MHC-II, and CD68, using immunofluorescence at various time points after infection." (PMID 37376550, 2023). "Additionally, the immunohistochemical staining of brains isolated from infected mice on Day 42 revealed an increased expression of CD68 by ~5-fold compared to the uninfected mice, indicating microglia activation at this late stage of infection." (PMID 38257755, 2023).
infection (continued). "In addition, the CM-resistant phenotype of CD68 KO mice is not due to reduced parasite hepatocyte load because the CM-resistant phenotype of CD68 KO mice is maintained even with similar parasite liver burdens of artificially high-dose infections (2 × 104)." (PMID 35073748, 2022). "However, qRT-PCR assays with 2 × 103 sporozoite injection show that liver invasion of CD68 KO mice is reduced by ∼70% compared with WT controls, which implies that lower-dose, natural-like infection mainly relies on the CD68-dependent transcytosis." (PMID 35073748, 2022). "In this study, we cloned and characterized the M. amblycephala CD68 (MaCD68) gene, analyzed the evolutionary characteristics of the CD68 gene in fish, and detected the expression and distribution of the MaCD68 gene and protein before and after infection." (PMID 36361921, 2022). "This CD68 expression was positively correlated with the intensity of the infection." (PMID 35387656, 2022). "CD68+ macrophages and elastase-positive neutrophils were detected in the liver and spleen sections of both the PbANKA group and the T. spiralis + PbANKA group on day 13 post-PbANKA infection." (PMID 32883347, 2020). "A significant upsurge in the number of CD68+ cells were detected in both groups of infected placentae (ZIKV+MIC– and ZIKV+MIC+), which suggested a recruitment of macrophages and hyperplasia caused by the infection in the basal decidua and Hofbauer cells." (PMID 32983175, 2020). "In addition to identifying p24+ CD3+ lymphocytes, as expected, we observed infection of CD68+ macrophages." (PMID 31805155, 2019). "CD68(bcl2)tg mice infected with L. pneumophila had significantly increased damage in their lungs compared to littermate controls as soon as 48 hours after infection and this damage was even greater 96 hours after infection in transgenic mice." (PMID 27973535, 2016). "However, only statistically significant modest decrease in CD68+ macrophage infiltration at later times after infection (28 dpi) into the hearts of infected Slamf1−/− compared to BALB/c mice were observed." (PMID 22807679, 2012). "We found that the main sources of IFNγ under infection were CD11c+ and CD68+ cells." (PMID 22815907, 2012). "Pathophysiological hypotheses include viral entry into the central nervous system and infection of peripheral CD68+ cells; viral proteins may have neurotoxic effects and HCV may directly affect serotonergic and dopaminergic neurotransmission with possible depressive symptoms." (PMID 40868568, 2025). "Interestingly, while microglia downregulated nominally phagocytic genes, Cd68, Mertk and Trem2, following infection, MG4 and MG5 upregulated the TAM receptor Axl which can recognize apoptotic and virus-infected cells expressing phosphatidylserine, potentially enhancing viral clearance." (PMID 37016414, 2023). "The colocalization rate of LC3‐II and CD68 in infected diabetic rats was 84.51 ± 4.22%, significantly higher than that in noninfected diabetic infected rats (44.32 ± 2.67%; p < .05), and meant that infection can trigger autophagy of dermis macrophages in diabetic rats." (PMID 34647429, 2021). "The condensing of the granuloma likely represents the removal of CD68+ phagocytes that successfully cleared fungal cells, while the recruited CD4+ T cells remain surrounding areas of ongoing infection." (PMID 39807873, 2025). "Infection with Hp suppressed the development of bleomycin-induced dermal fibrosis and the infiltration of CD3+ T cells and CD68+ macrophages." (PMID 39789188, 2025). "Specifically, we determined the distribution of lymphocytes (CD3), NK cells (CD56), monocytic phagocytes (CD68), and myeloid-derived suppressor cells (MDSC; CD11B and CD33) in the lungs at 2 and 4 weeks post infection." (PMID 38338937, 2024).
infection (continued). "At 24 h post-infection, cultures were dissociated by papain digestion, and live cells were surface-labeled with anti-GABA, anti-Glast, anti-GalC, and anti-CD68 antibodies targeting neurons, astrocytes, oligodendrocytes, and microglial cells, respectively." (PMID 36680268, 2023). "After 24 h, we observed that some CD68+ macrophages were positive for HIV-p24, multinucleated and positive for the CD3 T cell marker, demonstrating that in situ infection of macrophages by fusion with HIV-1-infected Jurkat cells was possible." (PMID 36988579, 2023). "Rarely, CD68+ macrophages contained SARS-CoV-2 NP as detected by immunofluorescence, resulting from either primary infection or secondary phagocytosis." (PMID 37205380, 2023). "A decrease was also detected in the surface area covered by dendritic cells (OX62+), macrophages and monocytes (CD68+), granulocytes (HiS48+), and endothelial cells (CD31+) compared with the early observation (day 8) after the initial infection." (PMID 35625758, 2022). "The expression of CD11b, CD4, CD14, and CD68 for M0; IL-6, HLA/DRA, and CXCL10 for M21, and IL-10, CD163, fibronectin-1 or FN1, and CCL17 was evaluated by qPCR at 2 and 24 h after infection." (PMID 35889103, 2022). "CD68 macrophages are more permissive to SIV infection than Mac387 cells, but their infection is temporally regulated." (PMID 35203323, 2022). "Considering the rapid drop in viral load after day 5 and increased frequency of CD68+ cells in the lung organoids of infected mice, we hypothesize that infiltrating human macrophages and to some degree neutrophils may play a key role in the rapid clearance of infection in our model." (PMID 36298826, 2022). "Quantitative analysis of HIV-1SF33-infected cells showed that hBD-2PTD and hBD-3PTD reduced the infection of CD4+ T lymphocytes, CD68+ macrophages, and CD1c+ DC by 20–70% compared with untreated tissues." (PMID 34696473, 2021). "Over the course of infection, the total microglia population progressively downregulated CX3CR1, F4/80, TMEM119 and CD68, and progressively upregulated CD45." (PMID 34311763, 2021). "The interaction of CD68+cells with HEV-3 antigen and parenchymal NO production seems to control infection and tissue damage during convalescence, predominantly in animals infected with swine source of HEV." (PMID 31211801, 2019). "Weak hepatic expression of CD68 was observed in B6.WT and B6.TNF−/− control groups, which was upregulated at day 42 after infection compared to its B6.WT counterpart." (PMID 29403488, 2018). "Our findings are consistent with a previous study, which used immunohistochemistry to detect HIV in human cervix 7 days post-infection and reported that HIV p24 Ag+ cells were predominantly CD14+/CD68+ cells and only a few were CD3+ T cells." (PMID 30532754, 2018). "One week post-infection, MDM were immunoassayed for HIV-1p24 (red) and macrophage marker CD68 (green)." (PMID 24662979, 2014). "Following infection of OVA-sensitized and -challenged mice, we found that RV colocalized with eotaxin-producing, CD68+ lung macrophages." (PMID 24907978, 2014). "As detected by immunohistochemistry, macrophages (CD68+) and activated HLADR+ presenting cells increased in PfHRP2+-placenta (p < 0.001 for both, DNS), mainly during late infection (CI or PI versus Ctrl: MW p < 0.001)." (PMID 20144201, 2010). "Total CD68 and CD14 prevalence increased over time after infection in RF-Bcl6no/lo tissues only, suggesting that macrophage accumulation and prolonged inflammation could contribute to sustained TNF-driven immune regulation." (PMID 40924502, 2025). "We also observed schistosome (but not L. donovani) infection led to marked reductions in BM CD68+ macrophages." (PMID 41296814, 2025).
infection (continued). "To examine expression of phospho-p38 in activated brain macrophages post WNV-E218A infection we stained 10 DPI CNS tissue for phospho-p38, the pan-macrophage marker Iba1, and the phagolysosomal marker CD68, a marker expressed highly on brain macrophages during WNV-induced synaptic stripping." (PMID 37983247, 2023). "However, ZIKVMR766 infection induced higher MHC-II and CD68 expressions when compared to ZIKVPE243 infection." (PMID 37376550, 2023). "We show that the CM-resistant phenotype of CD68 KO mice is mediated by soluble plasma factors generated during liver stage infection, independent of sporozoite numbers used for the challenge." (PMID 35073748, 2022). "Minimal or no overlap was observed between viral RNA and GFAP or CD68, indicating minimal or no infection in the astrocytes and microglia, respectively." (PMID 35533188, 2022). "In the absence of the receptor in CD68 knockout (KO) mice, sporozoite liver invasion occurs by breaching the two cell types lining the liver vessels - endothelial and Kupffer, reducing infection is by ∼70% compared with wild type (WT) controls." (PMID 35073748, 2022). "as an infiltrate of CD68+ mononuclear cells occupying ≥5% of the intervillous space “in the absence of clinical or histopathological signs of infection”." (PMID 35529853, 2022). "Surprisingly, we found that CM incidence of CD68 KO mice is substantially reduced compared to WT controls when mice are infected with sporozoites but importantly, not when bypassing the liver by infection with iRBCs." (PMID 35073748, 2022). "Notably, the majority chemokine ligand, which induced cells of the immune system to enter the site of infection, CCL-2, CD80 and CD68 of TAMs, IRF5 and NOS2 of M1, CD163 and MS4A4A of M2 were strongly related to JAK1 expression in LUAD (all P value < 0.0001)." (PMID 34587898, 2021). "The specific genes in the geneset that associated with the greatest odds of reduced risk of infection including SEMA4A, CTSD, CD68, and GAA were all members of this pathway, but not TNFSF13 (APRIL) which was the most protective gene in the NHP studies." (PMID 34533134, 2021). "The positive area of CD68 in the PVNF-5 group was the least, indicating that VA could be released from the composite films and play an anti-infection role." (PMID 34869271, 2021). "The number of cells with double staining for EIF5AHyp and CD68 was significantly increased in tissues from infected patients compared with individuals without infection." (PMID 33326776, 2020). "We therefore subjected FV-mWasabi+ CD68+ cells to a t-SNE analysis, which revealed a rather stable FV-mWasabi-infected MΦ population in lymph nodes, whereas the MΦ population in FV-mWasabi-infected spleens and bone marrow changed over the course of infection." (PMID 30782653, 2019). "In the adrenal gland, infection was restricted to the cortex, with MV-infected foci showing hemorrhagic necrosis and infiltration by CD68-expressing cells (data not shown)." (PMID 29743202, 2018). "As with tissue injury, microglial upregulation of CD68 in response to programmed cell death during development prepares the cell to become phagocytic, whereas upregulation of MHC-II plays a role in immunity against foreign antigens in infection." (PMID 24459672, 2013). "The results using CD68 and CD163 indicate that following SIV infection expression levels are increased 43 weeks post SIVmacJ5 or SIVmacC8 challenge with the highest expression levels being found 23 weeks post SIVmac17E-Fr infection." (PMID 22403025, 2012). "This approach uncovered a unique macrophage phenotype (IBA-1+CD68+CD206−CD163−) that localized to LN GCs and contained detectable HIV proteins, highlighting a novel pro-inflammatory macrophage subset with the potential to sustain infection within this immune-privileged microenvironment." (PMID 41542059, 2026).